GFAP (glial fibrillary acidic protein)
Diseases named in the same sentence as GFAP in open-access papers (continued):
Sharing a sentence is not in itself a finding about the gene and the disease.
ischemic stroke (continued). "Data from mice lacking GFAP and vimentin (GFAP−/−Vim−/−) and other experimental modulations of reactive gliosis point to reactive gliosis as protective in ischemic stroke, neurotrauma, and neurodegenerative diseases." (PMID 31480524, 2019). "A multicentre study focusing on S100β protein, NSE, GFAP and activated protein C–protein C inhibitor complex demonstrated the ability of GFAP to differentiate haemorrhagic stroke from ischaemic stroke, which has not been observed for other proteins." (PMID 25029344, 2014). "In GFAP–/– Vim–/– mice, astrocytes do not form cytoplasmic intermediate filaments, the reactive gliosis is impaired, and the infarcts developing after ischemic strokes are larger." (PMID 40747269, 2025). "Second, in our in vivo experiments, we focused exclusively on GFAP‐labeled astrocyte activation without evaluating the contributions of other critical cell types (e.g., microglia, neurons, or endothelial cells) to the pathophysiology of ischemic stroke." (PMID 40790939, 2025). "In the comparison of hemorrhagic and ischemic stroke based on GFAP status (positive vs. negative), post hoc power analysis using G*Power showed a power of 94.9% for an observed difference of 75.0% vs. 27.0% GFAP +, at a significance level of α = 0.033." (PMID 40649119, 2025). "Considering that both microglia and astrocytes are activated and sustained for many days in ischemic strokes, the timepoint of day 3 after surgery was used to clarify the cell specificity of hippocampal DAAO in ischemic mice by immunocolocalizing with Iba-1, NeuN, or GFAP, respectively." (PMID 36429117, 2022). "Recombined reactive astrocytes, co-expressing EYFP or tdTom and GFAP (but not PDGFRβ), could be observed in the lesion rim as part of the glial scar across all ischemic stroke models." (PMID 34535655, 2021). "However, correlation between the size of lesion and GFAP serum concentration does exist in the case of hemorrhagic stroke and not for the ischemic stroke, but only after 2 h from its onset." (PMID 31701356, 2020). "Compared with the control group, GFAP+ astrocyte density was much lower in the mutant peri­infarct area, suggesting a decrease in reactive astrogliosis in VPS35CX3CR1 cortex, providing additional support for an attenuated ischemic stroke injury in the mutant cortex." (PMID 31771656, 2019). "Interestingly, the difference in GFAP expression between hemorrhagic and ischemic stroke has not been confirmed in Chinese cohort study, which provides evidence for existing ethnic differences that should be taken into consideration by analyzing different population studies." (PMID 31701356, 2020). "Interestingly, both NEX+ neurons and GFAP+ astrocytes in the peri‐infarct region exhibited elevated Swell1 expression compared to the undamaged side, suggesting that neuronal and astrocytic SWELL1 channels may play an important role in the pathogenesis of ischemic stroke." (PMID 39056405, 2024). "GFAP, but not S100B or NSE, allowed to differentiate between ICH and ischemic stroke." (PMID 33115334, 2021).
brain injury (125 papers, 2008 to 2026). Acute and chronic (see also brain INJURIES, CHRONIC) injuries to the brain, including the cerebral hemispheres, CEREBELLUM, and brain STEM. "The astrocyte-associated intermediate filament protein glial fibrillary acidic protein (GFAP) has shown considerable promise as a blood-based biomarker for the detection of intracranial pathology following acute brain injuries." (PMID 40650780, 2025). "The Banyan Biomarkers' Brain Trauma Indicator (BTI) is an in‐vitro diagnostic test for the measurement of GFAP in the serum of suspected mild patients with traumatic brain injury." (PMID 39289040, 2025). "In this study, total tau and glial fibrillary acidic protein levels were associated with return to sport in male and female collegiate athletes following a sports-related concussion." (PMID 32852552, 2020). "This is supported by studies that have linked high GFAP serum levels in patients with traumatic brain injury." (PMID 30667110, 2019). "Pyruvate treatment of rats subjected to TBI for 72 h caused significant stimulation of PDH E1-∞ and less GFAP expression (marker of gliosis-brain injury) in comparison to the injured area with vehicle treatment [lower magnification: 25×]." (PMID 19561963, 2009). "Perhaps more important in terms of both research and clinical utility is the finding that, beyond SCAT-3 symptom severity score, GFAP at the acute postinjury time point was associated with greater classification of athletes with concussion, contact sport controls, and non–contact sport controls." (PMID 31977061, 2020). "Beyond SCAT-3 symptom score, GFAP at the acute postinjury time point was associated with the classification of athletes with concussion from contact controls (β = 12.298; 95% CI, 2.776-54.481; P = .001) and non–contact sport controls (β = 5.438; 95% CI, 1.676-17.645; P = .005)." (PMID 31977061, 2020). "Also, glial fibrillary acidic protein (GFAP), a marker of acute stroke and brain trauma, is significantly upregulated and associated with performance IQ, but not verbal IQ in “steady state” SCD patients with and without SCI." (PMID 31474929, 2019). "Fluctuation of GFAP, Nf-L, and particularly Aβ peptide levels may have utility as acute, systemic responders of subconcussive OP exposure caused by rifle fire even in the absence of extreme operational deficits or clinically defined concussion." (PMID 32849168, 2020). "GFAP is also a potentialpredictor of concussion status or increased RHI severity, albeit more-so in an acutepost-TBI timeframe." (PMID 40666430, 2025). "For example, traumatic brain injury reduces clearance via the glymphatic system which has been shown to suppress TBI‐induced increases of GFAP in the blood, which negatively impacts its clinical utility." (PMID 39289040, 2025). "The combined measurement of GFAP and UCH-L1 provides complementary insights into glial and neuronal damage and forms the basis of the Banyan Brain Trauma IndicatorTM, the first FDA-approved in vitro diagnostic test for TBI." (PMID 41465583, 2025). "Similar GFAP elevations have been observed in individuals exposed to high-altitude hypoxia and mild brain injuries, further supporting the link between flight stressors and neuroinflammation." (PMID 39766495, 2024). "This systematic review highlights the role of glial fibrillary acidic protein (GFAP) as a significant biomarker in the post-mortem analysis of traumatic brain injury (TBI)." (PMID 39796043, 2024). "Plasma p-tau181 levels within 6 h of sport-related injury showed similar diagnostic accuracy to GFAP, NFL, and UCH-L1 in discriminating military service academy cadets with combat-related concussion from uninjured cadets at the acute post-injury phase (<6 h)." (PMID 37662031, 2023). "A handheld blood test is now on the market for diagnosis of concussion based on the specific blood biomarkers glial fibrillary acidic protein (GFAP) and ubiquitin carboxyl terminal hydrolase L1 (UCH-L1)." (PMID 37958226, 2023).
brain injury (continued). "The microglial cell activation marker is CD11b, and GFAP is the biomarker for astrocyte stimulation which is induced due to brain injuries or stress to the central nervous system." (PMID 35625041, 2022). "Diagnostic aids for TBI based on GFAP and another blood-based biomarker– ubiquitin C-terminal hydrolase-L1 (UCH-L1) – have recently obtained regulatory approval (Banyan Brain Trauma Indicator Test." (PMID 35717463, 2022). "Only the association between acute GFAP level and 24- to 48-hour BESS score was statistically significant among cadets in the concussion group (r = 0.36; P = .049)." (PMID 33616662, 2021). "The results confirm the previous observation of hippocampal immunopositivity for GFAP in neurons following traumatic brain injuries." (PMID 34114049, 2021). "Our measurements demonstrated a trend toward elevated plasma GFAP within the concussion cohort (median 0.6 ng/ml; IQR 23.1; n = 11), when compared to their matched healthy control subjects (median 0.0 ng/ml, IQR 6.2; n = 17; P = 0.072)." (PMID 34987469, 2021). "GFAP is a cytoskeletal protein used as a specific marker to identify astrocytes in a reactive state because of a wide variety of brain injuries." (PMID 30732602, 2019). "In the present study, the IL-1β stimulation triggered an elevated level of GFAP and induced the astrocyte hypertrophy; this phenomenon was confirmed by the lesion site in a traumatic brain injury." (PMID 28356158, 2017). "Similar studies have shown that when induced to differentiate, IFN-γ drives NSC into a dysfunctional neuronal phenotype that express GFAP potentially skewing the reparative processes in response to brain injury." (PMID 25133679, 2014). "What makes GFAP specific to brain trauma is that even if the body is subjected to multiple forms of trauma, GFAP doesn’t spike up without brain injury." (PMID 23750150, 2013). "In conclusion, the Upfront DX LVOne GFAP LFA is sensitive for the detection of elevated serum GFAP levels, and as such, may be a useful adjunct to the care of patients with acute brain injuries in the pre-hospital setting." (PMID 40650780, 2025). "This may improve the accuracy of the test, particularly for mild TBI cases or regarding the diagnosis of sports-related concussion, where clinically important GFAP elevations are seen below the current detection threshold of the test." (PMID 40650780, 2025). "Glial fibrillary acidic protein (GFAp) is an astrocytic cytoskeletal protein upregulated in activated astrocytes, recognized for its swift elevation in both CSF and serum in response to acute brain injuries." (PMID 38385031, 2024). "For example, the increase in GFAP and NF-L levels among collegiate football players, regardless of their diagnosed concussions, echoes the previous findings on the sensitivity of these biomarkers to brain injuries." (PMID 38397046, 2024). "Moreover, the FDA has already approved the use of commercial GFAP assays for screening of brain trauma/concussions, and similar proteomic assays (e.g. serum NfL levels) are currently being reviewed for their use in multiple sclerosis disease monitoring." (PMID 37361716, 2023). "Though these results appear to be at odds, it has been well established that brain injuries and other stimuli that affect the astroglia cytoskeleton expose epitopes on GFAP that render it more readily detectable immunohistochemically without changes in GFAP content." (PMID 37095853, 2023). "EV levels of neurofilament light chain (NfL), a neurofilament protein and marker of axonal injury or degeneration, and glial fibrillary acidic protein (GFAP), a filament protein found in astrocytes, were higher in patients with diffuse brain injury than those with focal injury." (PMID 36636744, 2022). "Furthermore, a recent study on the temporal profile of biomarkers in sports-related concussion suggests that elevations of GFAP, NFL and tau are more likely to occur even days after injury, although there was not an acute measurement in that study." (PMID 35665051, 2022).
brain injury (continued). "GFAP, total tau, and NfL were increased after sport-related concussion vs. baseline." (PMID 33115334, 2021). "GFAP and tau were increased in male footballers with concussion at 2- and 13-days respectively." (PMID 33422120, 2021). "GFAP is believed to have a relatively stable release kinetic profile, with peak levels occurring approximately 20 h post injury in cases of mild to moderate traumatic brain injury and 1–2 days following incidents of severe traumatic brain injury." (PMID 31906443, 2020). "GFAP is a biomarker for traumatic brain injuries (TBI): this biomarker may predict the severity of injury." (PMID 31263455, 2019). "It was suggested that increased GFAP level may serve as a marker of axonal damage in patients with chronic neuropathies and with traumatic brain injuries." (PMID 29571287, 2018). "NFL, GFAP and T-tau are specific markers for damage of the central nervous system and increased concentrations of NFL and GFAP have previously been found both after acute and chronic brain injuries caused by different types of trauma." (PMID 22496755, 2012). "Together, these findings suggest that plasma p-tau181 may provide better results in the diagnosis of SRC than total tau in the acute phase and that the combination of p-tau181 with GFAP, NFL, and UCH-L1 may potentially enhance the diagnostic accuracy of a multi-marker panel for mTBI/concussion." (PMID 37662031, 2023). "Brain injuries also trigger an extensive glial response, referred to as reactive gliosis, which is characterized by activation and proliferation of astrocytes and microglial cells accompanied by increased expression of glial fibrillary acidic protein (GFAP) and CD68, respectively." (PMID 34572573, 2021). "Acute GFAP and NfL suppression among symptomatic participants was surprising, and may appear to be contrary to the effects shown for concussed athletes, wherein biomarkers generally increase among cohorts with a clinically defined concussion." (PMID 31408492, 2019). "Followingtraumatic brain injury (TBI), astrocytes undergo mechanical damage andstimulation, releasing large quantities of GFAP into the bloodstream." (PMID 39801405, 2025). "Protein biomarkers, particularly GFAP and UCH-L1, have achieved sufficient clinical validation to enable routine use in acute care settings, as evidenced by FDA approval of the Banyan Brain Trauma IndicatorTM." (PMID 41465583, 2025). "The clinical relevance of this concept is underscored by regulatory validation: GFAP and UCH-L1 are components of the FDA-cleared Banyan Brain Trauma IndicatorTM for evaluating mild TBI in adults." (PMID 41465583, 2025). "In this test, a small amount of blood is applied to the i-STAT cartridge which is then used to measure the release of GFAP and UCH L1 into the peripheral blood stream within 24 h of traumatic brain injury." (PMID 41002922, 2025). "The occurrence of post-traumaticmental disorder was taken as the dependent variable, while family satisfaction,the severity of traumatic brain injury, and serum levels of MMP-9,S100-β, and GFAP were included as independent variables." (PMID 39801405, 2025). "This response is commonly observed in cases of traumatic brain injury (TBI), where GFAP serves as an indicator of astrocyte activation and cell injury." (PMID 39796043, 2024). "Some serum biomarkers, including glial fibrillary acidic protein (GFAP), have been identified as potential predictors of mortality in cases of CT-negative traumatic brain injuries." (PMID 38668127, 2024). "Reactive astrogliosis, delineated by increased expression of glial fibrillary acidic protein (GFAP), signifies astrocyte activation in response to stress and brain trauma." (PMID 38470728, 2024). "In this regard, specific proinflammatory cytokines, including IL-1β, IL-6, TNF-α, and IFN-γ, and markers of brain injuries, such as NFL and GFAP, have been proposed as etiological factors of SB/SI development." (PMID 38338174, 2024).
brain injury (continued). "Recently, using the Breakthrough Devices Program, UCH-L1 and GFAP were approved by the Food and Drug Administration (FDA) as the first blood-based biomarker called the Brain Trauma IndicatorTM (BTITM)." (PMID 38397046, 2024). "The early elevation of beta-synuclein and GFAP, contrasted with the gradual increase of NFL, offers a more nuanced understanding of the biomarkers’ response to brain injuries, enhancing the ability to differentiate between patients with and without a TBI." (PMID 38397046, 2024). "Lastly, the study involving United States military cadets further corroborates the responsiveness of GFAP and UCH-L1 to brain injuries, reinforcing their utility in diverse settings, including military training." (PMID 38397046, 2024). "These include proteins such as S100B, GFAP, and UCH-L1, which are being evaluated for their sensitivity and specificity in detecting brain injuries." (PMID 39796043, 2024). "The potential of GFAP in clinical diagnosis was proved in several multi-center studies when a GFAP and ubiquitin carboxy-terminal hydrolase L1 blood test was authorized by the FDA to be used in mild traumatic brain injury." (PMID 37168256, 2023). "The Banyan Brain Trauma Indicator (BTITM) from Banyan Biomarkers is based on optical detection (chemiluminescent ELISA) and measures GFAP and UCH-L1 in human serum." (PMID 37048647, 2023). "FDA approved Brain Trauma Indicator and i-STAT Alinity TBI plasma test to measure UCH-L1 and glial fibrillary acidic protein (GFAP) for determination of clinical need of a CT after mild TBI." (PMID 35370671, 2022). "In the present study, on day 14 after brain trauma, CHI resulted in a substantial decrease in the numbers of Crry+ cells (including GFAP+/Crry+ astrocytes) in the injured cortices of mice in the Control group (data not shown)." (PMID 29367701, 2018). "Circulating protein expressions of tau, NF-L, GFAP, TNFα, and IL8 were assessed in the two concussion cases." (PMID 29706930, 2018). "Recently, the U.S. Food and Drug Administration reviewed and authorized for marketing the Banyan Brain Trauma Indicators which are ubiquitin C-terminal hydrolase-L1 (UCH-L1) and glial fibrillary acidic protein (GFAP), to evaluate mTBI in adults." (PMID 29963002, 2018). "Several cytokines, glial proteins, and enzymes with elevated expressions, such as TGF-β1, S100B, GFAP and TG2, are highly suspected of being involved in traumatic brain injury (TBI), neuroinflammation and acute CT, and also in the pathogenesis of AD." (PMID 29273062, 2017). "This convincingly explains the finding of massively elevated GFAP blood values, within minutes after symptom onset in ICH and traumatic brain injury, respectively." (PMID 23626774, 2013). "Hence, the GFAP, and to a lesser degree, tau and UCH-L1, is raised in participants with greater degrees of unobserved (CT-occult) brain injury, with these participants reporting less mental health and HRQoL impairment." (PMID 39652812, 2025). "In addition to serum MMP-9, S100-β, and GFAP, other biomarkers likeneuron-specific enolase (NSE) are also elevated after traumatic brain injury,reflecting the extent of neuronal damage." (PMID 39801405, 2025). "However, two serum neuromarkers, glial fibrillary acidic protein (GFAP) and ubiquitin C-terminal hydrolase-L1 (UCH-L1), have been proven as indicators of brain trauma and AIS." (PMID 38540221, 2024). "As the promising candidate biomarkers, UCH-L1 and GFAP, in conjunction, have recently garnered approval from the US Food and Drug Administration (FDA) for the evaluation of intracranial injury in patients with traumatic brain injury." (PMID 39104593, 2024). "On this light, FDA, EMA and more recently NIH approved the inclusion of NB such as S100B, Ubiquitin carboxyl-terminal hydrolase L1a and glial fibrillary acidic protein (G-FAP) in clinical protocols of adult and pediatric diseases such as traumatic brain injury." (PMID 35643585, 2022).